NBPF14 (NBPF member 14)
Synonyms: DJ328E19.C1.1; AE5; NBPF
Tractability: PROTAC: ubiquitination databases record sites on it.
Gene: Protein-coding gene on chromosome 1 (148,531,385 to 148,679,742, reverse strand). Ensembl gene ENSG00000270629.
Subcellular location: Cytoplasm
Subcellular location (Human Protein Atlas): Cytosol; Primary cilium; Cytokinetic bridge; End piece; Golgi apparatus; Microtubules; Mid piece; Principal piece; Vesicles
Gene Ontology:
Cellular component: cytoplasm
Genetic constraint (gnomAD): Loss-of-function variants: 13 observed, 18.43 expected, observed/expected ratio (o/e) 0.71, 90% interval 0.46 to 1.12. The upper end of that interval is the gene's LOEUF score, 1.12, which puts it in group 4 of 6, group 1 being the genes least tolerant of losing a copy. Missense variants: 133 observed, 147.53 expected, observed/expected ratio (o/e) 0.9, 90% interval 0.78 to 1.04. Synonymous variants: 56 observed, 54.22 expected, observed/expected ratio (o/e) 1.03, 90% interval 0.83 to 1.29.
Homologues: Paralogues in human: NBPF10 (99% identical), NBPF20 (89% identical), NBPF19 (89% identical), NBPF26 (46% identical), NBPF12 (38% identical), NBPF9 (36% identical), NBPF8 (30% identical), NBPF1 (28% identical), NBPF11 (26% identical), NBPF15 (22% identical), NBPF3 (16% identical), NBPF4 (10% identical), and 1 more.
Diseases named in the same sentence as NBPF14 in open-access papers:
NBPF14 is named in the same sentence as 11 diseases in open-access papers, as found by Europe PMC text mining. Sharing a sentence is not in itself a finding about the gene and the disease. The quoted sentences say what the papers report.
microcephaly (2 papers, 2021 to 2025). A congenital or acquired developmental disorder in which the circumference of the head is smaller than normal for the person's age and sex. "The present functional data on NBPF14 and its genomic localization (close to NOTCH2NLB) between the two breakpoints of the 1q21.1 distal duplication/deletion syndrome suggest NBPF14 as a novel and likely important player in the macrocephaly/microcephaly associated with this syndrome." (PMID 40138416, 2025). "NOTCH2NLB and NBPF14 map to the 1q21.1 genomic region, which is associated with the 1q21.1 distal duplication/deletion syndrome, a neurodevelopmental disorder linked to various neurological symptoms including autism spectrum disorders, schizophrenia, microcephaly, and macrocephaly." (PMID 40138416, 2025). "Specifically, combining these organoids with rescue experiments involving NOTCH2NLB and NBPF14, either individually or together, using electroporation could be a fruitful approach to understand the role of these genes in the microcephaly associated with this syndrome." (PMID 40138416, 2025). "Moreover, as two other human-specific genes are directly adjacent to NOTCH2NLA and NOTCH2NLB—that is, NBPF10 and NBPF14, respectively—mutations affecting these genes could be potentially important contributors to microcephaly." (PMID 34063381, 2021). "NBPF14 (Neuroblastoma Breakpoint Family Member 14) is an interesting candidate for a role in microcephaly, not only as it co-evolved with NOTCH2NLB and is located in the chromosomal region that is associated with 1q21.1 distal syndrome, but also as it belongs to the NBPF gene family." (PMID 34063381, 2021).
myasthenia gravis (1 paper, 2019). Myasthenia gravis (MG) is a rare, clinically heterogeneous, autoimmune disorder of the neuromuscular junction characterized by fatigable weakness of voluntary muscles. "By comparing transcriptome of thymoma with and without myasthenia gravis, we found that 5 genes (PNISR, CCL25, NBPF14, PIK3IP1 and RTCA) were upregulated more than 2-fold, and that more than 30 genes were downregulated more than 2-fold." (PMID 30787364, 2019).
neuroblastoma (1 paper, 2018). Neuroblastoma (NB) is the most common solid, extracranial childhood tumor. "The segment, which is classified as amplified, maps to the neuroblastoma breakpoint family gene NBPF14, so-called because NBPF1 (1p36.13) was discovered in a screen for genes disrupted by a translocation in a neuroblastoma brain cancer patient's normal genome." (PMID 30397684, 2018).
ovarian carcinoma (1 paper, 2025). A malignant neoplasm originating from the surface ovarian epithelium. "Using independent ovarian cancer cohort (TCGA-OV) we also confirmed high frequencies of mutational alterations in the NBPF gene family including NBPF1, NBPF9, NBPF10, NBPF12 and NBPF14 (> 50%)." (PMID 41316472, 2025).
tumor (3 papers, 2014 to 2023). "Among the 5,291 coding somatic mutations found in an aggregate of 240 matched tumour/normal samples, we found 26 overlapping variants in SH-SY5Y inside 24 genes among which 9 were rare amino-acid changing mutations inside 7 genes (ALK, FOXD4L1, HLA-DRB1, NBPF10, NBPF14, PABPC3, TEKT4)." (PMID 25528190, 2014). "Additionally, we observed that tumor-cell-specific isoforms had slightly more exons (paired t-test P-value = 0.01), particularly in genes with more than 20 exons such as NBPF10, VPS13C, and NBPF14." (PMID 37433798, 2023).
cancer (1 paper, 2023). A tumor composed of atypical neoplastic, often pleomorphic cells that invade other tissues. "To further confirm functional proteins associated with drug efficacy and response, we identified 19 genes as cancer-related genes (CRGs) in PCa, whereas 15 were overlapped DEP/Gs, and four (TTN, NBPF14, AHNAK2, COL1A1) were the top mutated genes in PCMR." (PMID 37121942, 2023).
neurogenetic diseases (1 paper, 2024). "Regarding cDC1s, the genes associated with MHC II antigen presentation (HLA-DRB5, IFI30), immune activation (NAPSB), and developmental and neurogenetic diseases (NBPF14) were highly expressed in active TAO compared to NCs." (PMID 38728262, 2024).
NBPF14 also shares sentences with these, for which no sentence is quoted: autism spectrum disorder (1 paper); neurodevelopmental disorder (1); schizophrenia (1); thymoma (1).